EHD3 (EH domain containing 3)
Description:
ATP- and membrane-binding protein that controls membrane reorganization/tubulation upon ATP hydrolysis. In vitro causes tubulation of endocytic membranes. Binding to phosphatidic acid induces its membrane tubulation activity (By similarity). Plays a role in endocytic transport. Involved in early endosome to recycling endosome compartment (ERC), retrograde early endosome to Golgi, and endosome to plasma membrane (rapid recycling) protein transport. Involved in the regulation of Golgi maintenance and morphology. Involved in the recycling of internalized D1 dopamine receptor. Plays a role in cardiac protein trafficking probably implicating ANK2. Involved in the ventricular membrane targeting of SLC8A1 and CACNA1C and probably the atrial membrane localization of CACNA1GG and CACNA1H implicated in the regulation of atrial myocyte excitability and cardiac conduction (By similarity). In conjunction with EHD4 may be involved in endocytic trafficking of KDR/VEGFR2 implicated in control of glomerular function (By similarity). Involved in the rapid recycling of integrin beta-3 implicated in cell adhesion maintenance. Involved in the unidirectional retrograde dendritic transport of endocytosed BACE1 and in efficient sorting of BACE1 to axons implicating a function in neuronal APP processing (By similarity). Plays a role in the formation of the ciliary vesicle, an early step in cilium biogenesis; possibly sharing redundant functions with EHD1.
Synonyms: PAST3
Tractability: Antibody: UniProt places it where antibodies can reach, with high confidence; its Gene Ontology location is reachable by antibodies, with medium confidence; the Human Protein Atlas places it where antibodies can reach. PROTAC: UniProt records ubiquitination sites on it; ubiquitination databases record sites on it; its protein half-life has been measured.
Gene: Protein-coding gene on chromosome 2 (31,233,961 to 31,269,451, forward strand). Ensembl gene ENSG00000013016.
Subcellular location: Recycling endosome membrane; Cell membrane; Cell projection, cilium membrane
Subcellular location (Human Protein Atlas): Plasma membrane; Primary cilium; Primary cilium transition zone
Pathways (Reactome):
Hemostasis: Factors involved in megakaryocyte development and platelet production
Gene Ontology:
Molecular function: protein binding; nucleic acid binding; protein-macromolecule adaptor activity; calcium ion binding; GTP binding
Biological process: cilium assembly; early endosome to Golgi transport; endocytic recycling; Golgi to lysosome transport; protein homooligomerization; protein localization to plasma membrane; receptor recycling; regulation of cardiac muscle cell membrane potential; regulation of Golgi organization; regulation of cardiac conduction; regulation of cardiac muscle contraction
Cellular component: ciliary pocket membrane; ciliary transition zone; cilium; focal adhesion; plasma membrane; recycling endosome membrane; cytoplasm; early endosome; endocytic vesicle; endosome membrane; nucleus; perinuclear region of cytoplasm; ciliary membrane; cytosol
Genetic constraint (gnomAD): Loss-of-function variants: 17 observed, 44.1 expected, observed/expected ratio (o/e) 0.39, 90% interval 0.26 to 0.58. The upper end of that interval is the gene's LOEUF score, 0.58, which puts it in group 2 of 6, group 1 being the genes least tolerant of losing a copy. Missense variants: 594 observed, 740.73 expected, observed/expected ratio (o/e) 0.8, 90% interval 0.75 to 0.86. Synonymous variants: 313 observed, 305.86 expected, observed/expected ratio (o/e) 1.02, 90% interval 0.93 to 1.12.
Homologues: Orthologues: chimpanzee EHD3 (99% identical), macaque EHD3 (99% identical), guinea pig EHD3 (99% identical), dog EHD3 (98% identical), rat Ehd3 (98% identical), mouse Ehd3 (97% identical), pig EHD3 (97% identical), rabbit EHD3 (93% identical), zebrafish ehd3 (93% identical), tropical clawed frog ehd3 (93% identical), Drosophila melanogaster Eps-15 (14% identical), Caenorhabditis elegans itsn-1 (13% identical), and 2 more. Paralogues in human: EHD1 (87% identical), EHD4 (75% identical), EHD2 (72% identical), SRL (26% identical), ITSN1 (21% identical), ITSN2 (20% identical), EPS15L1 (18% identical), EPS15 (17% identical), REPS1 (12% identical), REPS2 (10% identical).
Diseases named in the same sentence as EHD3 in open-access papers:
EHD3 is named in the same sentence as 28 diseases in open-access papers, as found by Europe PMC text mining. Sharing a sentence is not in itself a finding about the gene and the disease. The quoted sentences say what the papers report.
glioma (3 papers, 2016 to 2024). A benign or malignant brain and spinal cord tumor that arises from glial cells (astrocytes, oligodendrocytes, ependymal cells). "We have recently identified Ehd3 as a new putative glioma tumor suppressor, whose loss of expression is a very frequent event in gliomas of all grades." (PMID 27811356, 2016). "Strongly decreased EHD3 expression levels were found in oral squamous cell carcinoma and gliomas, while EHD3 overexpression was found in a rat model of ischemic heart failure." (PMID 39074100, 2024). "Using a Dox-inducible system, we examined the impact of restoring EHD3 expression to two glioma cell lines that express very low levels of EHD3, i.e. the U251 and U87MG cells, on the expression of EGFR." (PMID 27811356, 2016). "In a recent work, we have shown that Ehd3 presents features of a glioma tumor suppressor gene." (PMID 27811356, 2016). "We have recently shown evidence that EHD3 possesses tumor suppressor functions in gliomas." (PMID 27811356, 2016). "EHD3 regulates endocytic recycling, along with other EHD family members, and it has been considered to be a tumor suppressor in gliomas." (PMID 31962291, 2020).
depression (2 papers, 2020 to 2021). "A previous study suggested that EHD3 polymorphism explains why women are more prone to major depressive disorder than men are." (PMID 33922189, 2021).
diabetes (2 papers, 2021 to 2024). "An in-depth analysis of the diseased fenestration phenotype revealed a downregulation in EHD3 in patients with diabetes, confirming the regulatory role of EHD3 in glomerular fenestration formation and maintenance as observed previously in mouse models." (PMID 39201792, 2024).
brain tumor (1 paper, 2016). "We have recently identified EHD3 [Eps15 homology (EH) domain-containing protein 3], an endocytic trafficking regulatory protein, as a putative brain tumor suppressor." (PMID 27811356, 2016).
breast carcinoma (1 paper, 2021). "From the TCGA dataset, only small portions of breast cancers (1.1%, 1/87), lung adenocarcinomas (6.9%, 2/29), and squamous cell lung cancers (0.0%, 0/40) had EHD3 hypermethylation." (PMID 33922189, 2021). "However, QMSP analysis of Taiwanese patients with esophageal and breast cancer revealed a lower aberrant frequency of the EHD3 promoter methylation level." (PMID 33922189, 2021). "EHD3 hypermethylation was at least twofold higher in tumors than in matched normal tissues in only 15.2% (5/33) of patients with lung cancer, 40.0% (8/20) of those with breast cancer, and 13.3% (2/15) of those with uterine cancer." (PMID 33922189, 2021).
chordoma (1 paper, 2021). Chordomas are rare malignant tumors arising from embryonic remnants of the notochord in axial skeleton. "In the primary chordoma tissue, a pathogenic mutation in EHD3 (rs772124528) was detected, which was also found in U-CH11R." (PMID 34330313, 2021).
esophageal cancer (1 paper, 2021). A primary or metastatic malignant neoplasm involving the esophagus. "In the Taiwanese cohort, EHD3 hypermethylation was detected in 73.1% (19/26) of patients with CRC and 18.8% (3/16) of patients with esophageal cancer compared with matched normal tissues." (PMID 33922189, 2021).
gastric cancer (1 paper, 2021). A primary or metastatic malignant neoplasm involving the stomach. "EHD3 promoter hypermethylation likely plays a vital role in gastrointestinal cancers, such as esophageal and gastric cancer, in Western populations." (PMID 33922189, 2021).
glomerular disease (1 paper, 2011). "We generated Ehd3–/–; Ehd4–/– mice to test this hypothesis and observed severe glomerular disease in these mice, demonstrating a critical role for EHD3 and EHD4 in glomerular health." (PMID 21408024, 2011).
heart failure (1 paper, 2015). Inability of the heart to pump blood at an adequate rate to meet tissue metabolic requirements. "Recent data has indicated that EHD3 is also increased in human heart failure and in all animal models of heart failure yet examined." (PMID 25709583, 2015).
juvenile polyposis syndrome (1 paper, 2010). Juvenile gastrointestinal polyposis (JIP) is a rare condition characterized by the presence of juvenile hamartomatous polyps in the gastrointestinal (GI) tract. "Since we found significant cancer-related pathways associated only with BMPR1A but not with WDTC1 or EHD3, and in addition germline mutations in BMPR1A are a known risk factor for juvenile polyposis syndrome, we chose BMPR1A for additional functional assays." (PMID 21203531, 2010).
lung carcinoma (1 paper, 2021). "EHD3 mRNA expression in CRC cell lines was also lower than that in normal tissues and breast and lung cancer cell lines." (PMID 33922189, 2021).
melanoma (1 paper, 2022). A malignant, usually aggressive tumor composed of atypical, neoplastic melanocytes. "GSEA and expression analysis revealed that NGFR+ tumors indeed expressed high levels of MRD-associated genes, particularly the MRD-associated gene EHD3 was upregulated in post-treatment melanoma and was significantly more highly expressed in NGFRhigh MBM." (PMID 36435874, 2022). "Next, we investigated the representation of Ecad and NGFR gene signatures in pre- and post-BRAFi/MEKi treated melanoma and observed a significant upregulation of NGFR-core genes such as EHD3 (p = 0.042)." (PMID 36435874, 2022).
thrombotic microangiopathy (1 paper, 2011). The syndromes of microangiopathic hemolytic anemia, thrombocytopenia, and variable signs of organ impairment, due to platelet aggregation in the microcirculation. "H&E and PAS staining of kidney sections from Ehd3–/–; Ehd4–/– mice showed lesions characteristic of thrombotic microangiopathy (TMA)." (PMID 21408024, 2011). "Detailed analyses of Ehd3–/–; Ehd4–/– kidneys demonstrated thrombotic microangiopathy (TMA)-like glomerular lesions including thickening and duplication of glomerular basement membrane, endothelial swelling and loss of fenestrations." (PMID 21408024, 2011).
tumor (6 papers, 2004 to 2023). "Multivariate Cox proportional-hazards survival analysis indicated that EHD3 hypermethylation was independently and significantly associated with overall survival after adjustment for age, location, tumor size, lymph invasion, and metastasis (p = 0.039)." (PMID 33922189, 2021). "Using the TCGA data from colon, rectal, gastric cancer patients and their own results of the Illumina Methylation 450K BeadChip array analysis of a CRC patient tumor and normal tissues, the authors selected EHD3, TMEM240, and SMAD3 as promising tumor markers." (PMID 37569782, 2023). "EHD3 mRNA expression was at least 2-fold lower in tumor tissues than in normal tissues in 45.1% (46/102) of the paired tissues." (PMID 33922189, 2021). "At first examination, the finding that a putative tumor suppressor (i.e. EHD3) increases the levels of an oncogene (i.e. EGFR) appears counterintuitive." (PMID 27811356, 2016). "In summary, this is the first report supporting a mechanism of EHD3-mediated tumor suppression that involves the attenuation of endosomal signaling of the EGFR oncogene." (PMID 27811356, 2016). "We have previously reported, using a xenograft model of U251tetEHD3 cells implanted subcutaneously in nude mice, that EHD3 expression reduces tumor growth in vivo." (PMID 27811356, 2016). "The promoter and exon 1 regions of EHD3 in CRC tumor tissues exhibited 21 highly methylated sites." (PMID 33922189, 2021). "Therefore, EHD3 can not only be developed as a prognostic marker but also as a tumor biological factor for chemotherapy response." (PMID 33922189, 2021). "In addition, 64.7% and 55.4% of patients with CRC had threefold and fivefold higher EHD3 hypermethylation in tumor tissues, respectively." (PMID 33922189, 2021). "In summary, our data suggest that EHD3 might undergo its tumor suppressor functions at least in part through promoting the sorting of activated EGFR to the lysosomal degradative compartment and spatio-temporal regulation of EGFR signaling via ERK and AKT." (PMID 27811356, 2016). "Analysis of RNA and protein data indicated that EHD3 RNA and protein expression was significantly reduced in CRC tumor tissues compared with matched normal tissues (p = 0.029 and p < 0.001)." (PMID 33922189, 2021).
cancer (4 papers, 2010 to 2025). A tumor composed of atypical neoplastic, often pleomorphic cells that invade other tissues. "And most of the 24 DEPs (CDK1, SFN, PRKAR2B, MKI67 and MDK involved in the cell cycle; LOXL2, P4HA1, P4HA2, SPRX, DES, PRPH and CALML3 involved in construction and regulation of extracellular matrix; IL33 and EHD3 may involve in immune) were linked to cancer hallmarks." (PMID 33200655, 2020). "Patients with late-stage cancer and female patients with late-stage and low EHD3 protein expression consistently had poorer prognoses than did those with high EHD3 protein expression (p = 0.045 and p = 0.012)." (PMID 33922189, 2021). "Few reports on EHD3 hypermethylation in cancer have been published; therefore, EHD3 was selected for further analysis." (PMID 33922189, 2021). "Cancers originating outside the alimentary canal exhibited minimal EHD3 hypermethylation in both Western and Asian populations." (PMID 33922189, 2021). "For example, EHD3 promotes cancer progression by affecting the Wnt/β-catenin signalling pathway." (PMID 40564032, 2025). "Analysis of the EHD3 mRNA expression in gastrointestinal cancers might help elucidate the relationship between the EHD3 anomaly and cancer development." (PMID 33922189, 2021). "Furthermore, looking at intersections between both cancer types we found BMPR1A, WDTC1 (WD and tetratricopeptode repeats 1) and EHD3 (EH-domain containing 3) mutated in both tumors." (PMID 21203531, 2010).
colonic polyps (1 paper, 2021). "In the Asian cohort, Eps15 homology domain-containing protein 3 (EHD3) had twofold higher methylation in 44.4% of patients with colonic polyps, 37.3% of plasma from CRC patients, and 72.6% of CRC tissues, which was connected to vascular invasion and high microsatellite instability." (PMID 33922189, 2021).
infection (1 paper, 2018). The state of being infected such as from the introduction of a foreign agent such as serum, vaccine, antigenic substance or organism. "Further, a number of these CIE regulators, including Rab11a, Hook1, ACAP1/2, and EHD3, are targeted by microRNAs or downregulated by infection with HCMV." (PMID 30042195, 2018).
mental illness (1 paper, 2021). "Therefore, another explanation for correlation between EHD3 hypermethylation and poor prognoses is that women with CRC and EHD3 hypermethylation may present signs of mental illness, leading to a poor prognosis." (PMID 33922189, 2021).
EHD3 also shares sentences with these, for which no sentence is quoted: cardiac ischemia (1 paper); colon cancer (1); liver cancer (1); lung adenocarcinoma (1); oral squamous cell carcinoma (1); pancreatic cancer (1); rectal cancer (1); squamous cell lung carcinoma (1); uterine cancer (1).